ASPHD1 (aspartate beta-hydroxylase domain containing 1)
Tractability: Antibody: UniProt predicts a signal peptide or a membrane-spanning region.
Gene: Protein-coding gene on chromosome 16 (29,900,375 to 29,919,864, forward strand). Ensembl gene ENSG00000174939.
Subcellular location: Membrane
Gene Ontology:
Cellular component: membrane
Genetic constraint (gnomAD): Loss-of-function variants: 17 observed, 23.14 expected, observed/expected ratio (o/e) 0.73, 90% interval 0.5 to 1.1. The upper end of that interval is the gene's LOEUF score, 1.1, which puts it in group 4 of 6, group 1 being the genes least tolerant of losing a copy. Missense variants: 475 observed, 479.29 expected, observed/expected ratio (o/e) 0.99, 90% interval 0.92 to 1.07. Synonymous variants: 239 observed, 201.81 expected, observed/expected ratio (o/e) 1.18, 90% interval 1.07 to 1.32.
Homologues: Orthologues: chimpanzee ASPHD1 (99% identical), macaque ASPHD1 (92% identical), dog ASPHD1 (87% identical), guinea pig ASPHD1 (84% identical), rat Asphd1 (82% identical), mouse Asphd1 (82% identical), zebrafish asphd1 (41% identical), Drosophila melanogaster Asph (18% identical), Caenorhabditis elegans K09A9.6 (15% identical). Paralogues in human: ASPHD2 (41% identical), ASPH (22% identical).
Diseases named in the same sentence as ASPHD1 in open-access papers:
ASPHD1 is named in the same sentence as 17 diseases in open-access papers, as found by Europe PMC text mining. Sharing a sentence is not in itself a finding about the gene and the disease. The quoted sentences say what the papers report.
schizophrenia (2 papers, 2021 to 2023). A major psychotic disorder characterized by abnormalities in the perception or expression of reality. "ASPHD1 (Aspartate Beta-Hydroxylase Domain Containing 1) is another gene linked with schizophrenia (specifically, Schizophrenia 3)." (PMID 37486921, 2023). "Furthermore, SEZ6L2, CDIPTOSP, ASPHD1, and RANBP1 are potential candidate genes for schizophrenia." (PMID 37486921, 2023).
skin cutaneous melanoma (2 papers, 2023 to 2025). "Pan-cancer analysis further revealed that higher ASPHD1 expression was associated with longer OS in skin cutaneous melanoma (SKCM), uveal melanoma (UVM), and mesothelioma (MESO)." (PMID 41551155, 2025).
cholangiocarcinoma (1 paper, 2023). A carcinoma that arises from the intrahepatic biliary tree (intrahepatic cholangiocarcinoma) or from the junction, or adjacent to the junction, of the right and left hepatic ducts (hilar cholangiocarcinoma). "Finally, as far as we know, there have been a few studies focusing on ASPH and cancers, such as pancreatic ductal adenocarcinoma, hepatocellular carcinoma, and cholangiocarcinoma, but this is the first report on the relationship between ASPHD1 and melanoma." (PMID 37004045, 2023).
colorectal cancer (1 paper, 2023). A primary or metastatic malignant neoplasm that affects the colon or rectum. "Our data show the prognostic value of ASPHD1 and ZBTB12 in CRC, warranting further investigations to validate their clinical potential as prognostic markers and predictive markers for colorectal cancer." (PMID 37686578, 2023).
glioma (1 paper, 2025). A benign or malignant brain and spinal cord tumor that arises from glial cells (astrocytes, oligodendrocytes, ependymal cells). "By performing a comprehensive analysis, we evaluate the genomic interaction networks associated with ASPHD1 in glioma and further explore its function in intratumor communication." (PMID 41551155, 2025). "The diagnostic value of ASPHD1 in gliomas was first assessed using ROC (Receiver Operating Characteristic) curves." (PMID 41551155, 2025). "High ASPHD1 expression is associated with less aggressive glioma phenotypes and a more neuron-like, differentiated state, possibly mediated through synaptic signaling, ion-channel, and calcium-related pathways." (PMID 41551155, 2025). "ASPHD1 appears to be a favorable prognostic biomarker in glioma and may have potential diagnostic value, although its performance as a stand-alone marker is modest and requires further validation." (PMID 41551155, 2025). "Multivariate regression analysis indicated that low ASPHD1 expression (hazard ratio, 0.999; 95% confidence interval, 0.997–1.000, P < 0.05), older age (hazard ratio, 1.060; 95% confidence interval, 1.027–1.093, P < 0.001) and higher grade (P < 0.001) were independent risk factors of gliomas." (PMID 41551155, 2025). "In our study, we initially showed reduced levels of ASPHD1 in glioma tissue compared to normal tissues, followed by evaluating its diagnostic and prognostic value through extensive computational biology analysis." (PMID 41551155, 2025). "The initial quantification of ASPHD1 transcriptional abundance was conducted within TCGA, consisting of a cohort of 674 glioma samples and 5 normal samples." (PMID 41551155, 2025). "One limitation of the current study is that the fundamental biochemical and cellular functions of ASPHD1 remain incompletely understood, even though our data support its role as a new prognostic indicator for glioma." (PMID 41551155, 2025). "In glioma cell lines, ASPHD1 overexpression suppressed proliferation, migration, and invasion in vitro, and inhibited tumor growth in a subcutaneous U87 xenograft model." (PMID 41551155, 2025). "Flow cytometric analysis revealed that ASPHD1 overexpression significantly altered the cell cycle distribution of both U87 and U251 glioma cells." (PMID 41551155, 2025). "Western blot analysis confirmed the successful overexpression of ASPHD1 protein in both U87 and U251 glioma cells." (PMID 41551155, 2025). "The findings demonstrated that elevated levels of ASPHD1 expression was associated with extended OS in SKCM, UVM, MESO, and low-grade glioma (LGG)." (PMID 41551155, 2025). "In our study, we investigated the levels of ASPHD1 in glioma patients by utilizing data from the TCGA, CGGA, and GEO databases." (PMID 41551155, 2025). "Together, these findings identify ASPHD1 as a favorable prognostic biomarker in glioma and suggest that high ASPHD1 expression restrains glioma progression while promoting neuron-like differentiation of glioma cells." (PMID 41551155, 2025). "The EdU proliferation assay revealed that overexpression of ASPHD1 significantly reduced the proliferation of both U87 and U251 glioma cells compared to the vector control groups." (PMID 41551155, 2025). "Colony formation assays were conducted to evaluate the long-term effects of ASPHD1 overexpression on glioma cell growth." (PMID 41551155, 2025). "These reciprocal findings from gain- and loss-of-function models support a specific role for endogenous ASPHD1 in restraining glioma cell proliferation and migration." (PMID 41551155, 2025). "ASPHD1 expression showed modest but significant ability to distinguish glioma from normal brain tissue, with areas under the curve (AUCs) of 0.646 in the TCGA cohort, 0.710 in the CGGA mRNAseq_325 cohort, and 0.641 in the CGGA mRNAseq_693 cohort." (PMID 41551155, 2025). "Taken together, these reciprocal changes in NeuN and GFAP expression suggest that ASPHD1 promotes neuronal-like differentiation in glioma cells." (PMID 41551155, 2025).
glioma (continued). "Finally, our functional data support a tumor-suppressive role of ASPHD1 and indicate that it promotes a neuron-like differentiated state in glioma cells." (PMID 41551155, 2025). "Additionally, immunohistochemistry indicated that staining for the ASPHD1 antibody was lighter in gliomas, suggesting low expression of this gene in glioma tissues." (PMID 41551155, 2025). "To investigate whether ASPHD1 overexpression promotes neuronal differentiation in glioma cells, we assessed the expression of NeuN, a well-established neuronal marker, in U251 and U87 cells." (PMID 41551155, 2025). "Our findings suggest that ASPHD1 may serve as a promising new candidate for the diagnosis and management of glioma." (PMID 41551155, 2025). "To determine whether ASPHD1 OE suppressed glioma cell–derived tumor growth in vivo, we established stable U87 cell lines by integrating an ASPHD1 OE vector or the control vector." (PMID 41551155, 2025). "Four immune cell subtypes (CD4+ naïve T cells, monocytes, macrophages M0 and activated NK cells) to be expressed differently between the two groups (H-ASPHD1 and L-ASPHD1), so immune infiltration may play a role between ASPHD1 and glioma." (PMID 41551155, 2025). "In U251 glioma cells we next examined whether ASPHD1 affects basic electrophysiological properties and Ca2+ signaling." (PMID 41551155, 2025). "Furthermore, ASPHD1 mRNA expression progressively decreased with increasing glioma grade." (PMID 41551155, 2025). "In the TCGA dataset, univariate regression analysis revealed that expression level of ASPHD1, whether radiation therapy was performed, age, tumor dimension, tumor location, tumor grade, and tumor pathological type were prognostic indicators in gliomas." (PMID 41551155, 2025). "Finally, we explored the functional roles of ASPHD1 in glioma, using the U251 and U87 cell models." (PMID 41551155, 2025). "Therefore, the in vivo effects of ASPHD1 on glioma progression observed here should be interpreted with caution, and future studies incorporating orthotopic intracranial models will be important to validate these findings under more physiologically relevant conditions." (PMID 41551155, 2025). "Therefore, further research may involve investigation of the specific mechanism by which ASPHD1 regulates glioma through these signaling pathways above." (PMID 41551155, 2025). "ASPHD1 is underexpressed in GBM, and also has a tendency to be underexpressed in lower grade glioma (LGG)." (PMID 41551155, 2025). "In CCGA325, univariate regression analysis showed that age, expression level of ASPHD1, whether radiation therapy was performed, presence or absence of the 1p19q co-deletion, IDH mutation, tumor grade, and whether the tumor was recurrent were prognostic indicators in gliomas." (PMID 41551155, 2025). "In glioma samples compared to normal tissues, patient groups from the TCGA, GEO, and CGGA databases exhibited reduced ASPHD1 mRNA levels." (PMID 41551155, 2025). "However, there is currently no relevant research on ASPHD1 in glioma." (PMID 41551155, 2025).
melanoma (1 paper, 2023). A malignant, usually aggressive tumor composed of atypical, neoplastic melanocytes. "Meanwhile, mRNA and protein levels of ASPHD1 from three human melanoma cell lines were much higher than that of human normal epidermal melanocytes according to qRT-PCR and western blot." (PMID 37004045, 2023).
cancer (3 papers, 2023 to 2025). A tumor composed of atypical neoplastic, often pleomorphic cells that invade other tissues. "In addition, pan-cancer analyses suggest that ASPHD1 expression is associated with prognosis in several other tumor types." (PMID 41551155, 2025). "To evaluate the potential widespread relevance of ASPHD1, we conducted a range of investigations on its expression across various cancers." (PMID 41551155, 2025). "Collectively, ASPHD1 and ZBTB12 are linked to multiple proteins and genes which are associated with cancer initiation and progression." (PMID 37686578, 2023). "The ASPHD1 expression level was significantly upregulated in several cancers, including SKCM especially SKCM-metastasis tissues, and patients with an increased ASPHD1 expression had longer overall survival time than low expression ones." (PMID 37004045, 2023). "To date, the relationship between ASPHD1 and cancers has been less studied, and its role in the occurrence and development of cancers is not clear." (PMID 37004045, 2023). "Among the 30 types of cancer examined, the prognosis of seven cancers was related to ASPHD1 levels." (PMID 41551155, 2025). "ASPHD1 may be involved in cancer progression through its control of alpha-ketoglutarate-dependent dioxygenases." (PMID 41551155, 2025). "However, as a critical paralog of ASPH, the relationship between ASPHD1 and cancer is less studied, and its role in the occurrence and progression of neoplasm is not clear." (PMID 37004045, 2023). "Aspartate beta-hydroxylase domain containing 1 (ASPHD1) may participate in cancer progression through controlling α-ketoglutarate-dependent dioxygenases." (PMID 37004045, 2023). "Also, Kaplan–Meier revealed that the overall survival of patients with cancer having low ASPHD1 expression had higher overall survival (OS) than patients with cancer with high ASPHD1 expression (p < 0.05)." (PMID 37686578, 2023). "Hence, further research should be carried out on the role of ASPHD1 in cancer." (PMID 37004045, 2023). "Data from the PPI network showed that ASPHD1 is related to several proteins and genes such as KIF22, INO80E, SEZ6L2, and DOC2A, most of which are cancer-related." (PMID 37686578, 2023). "The intrinsic mechanism of ASPHD1 in cancer onset and advancement is complex and not well understood." (PMID 41551155, 2025).
tumor (2 papers, 2023 to 2025). "The immunofluorescence results confirmed that xenografts in the ASPHD1 OE group exhibited elevated ASPHD1 expression levels compared with control tumors, consistent with the reduced tumor burden observed in mice bearing ASPHD1-overexpressing xenografts." (PMID 41551155, 2025). "In this work, we comprehensively analyzed the relationship between ASPHD1 expression and the clinical parameters, overall survival, and tumor immune microenvironment in SKCM." (PMID 37004045, 2023). "Our research additionally indicates that ASPHD1 expression does not show an association with tumor purity or immune infiltration." (PMID 41551155, 2025). "To verify whether ASPHD1 overexpression promotes tumor cell differentiation, we performed transcriptome sequencing analysis." (PMID 41551155, 2025). "Moreover, the relationship between ASPHD1 expression and lymphocytic infiltration in tumor immune microenvironments was also evaluated." (PMID 37004045, 2023). "ASPHD1 may participate in the regulation of tumor immune microenvironment." (PMID 37004045, 2023).
infection (1 paper, 2026). The state of being infected such as from the introduction of a foreign agent such as serum, vaccine, antigenic substance or organism. "coli infection via a novel host defense pathway involving upregulation of ASPHD1." (PMID 41751799, 2026).
ASPHD1 also shares sentences with these, for which no sentence is quoted: breast invasive carcinoma (1 paper); gastric cancer (1); glioblastoma multiforme (1); hepatocellular carcinoma (1); lung carcinoma (1); mesothelioma (1); pancreatic ductal adenocarcinoma (1); uveal melanoma (1).